RNU7-84P (RNA, U7 small nuclear 84 pseudogene)
Synonyms: U7.84
Gene: Small nuclear RNA gene on chromosome 8 (106,729,795 to 106,729,856, reverse strand). Ensembl gene ENSG00000251892.
Homologues: Orthologues: chimpanzee U7 (100% identical), macaque U7 (90% identical). Paralogues in human: U7 (90% identical), RNU7-65P (89% identical), RNU7-60P (85% identical), RNU7-188P (84% identical), RNU7-2P (84% identical), RNU7-35P (84% identical), RNU7-52P (84% identical), RNU7-55P (84% identical), RNU7-56P (84% identical), RNU7-79P (84% identical), RNU7-80P (84% identical), RNU7-88P (84% identical), and 142 more.